CD4 (CD4 molecule)
Diseases named in the same sentence as CD4 in open-access papers (continued):
Sharing a sentence is not in itself a finding about the gene and the disease.
infection (continued). "Here we showed that levels of M. tuberculosis-specific KRLG1+ CD4 and CD8 T cells were high early (20 dpi) after infection and decreased thereafter, while the levels of PD1+ T cells increased during the first weeks of infection, remaining high at later time points." (PMID 33193338, 2020). "Our results further indicate that CD4+CD25+ CD127- Treg cells show an increasing trend on 5 dpi, confirming their activation during the middle stage of infection, which may lead to immunosuppressive effects consistent with clinical reports." (PMID 33180882, 2020). "Airway memory CD4+ T cell mediate protective immunity in respiratory coronaviruses and it will be of particular interest to see if CoV2 specific CD4+ T cell in BAL can predict resolution of infection." (PMID 33133083, 2020). "Mice that did not exhibit sufficient percentages of human cells (< 65% of CD45+ cells and < 70% of CD3+ and CD4+ cells) were not used in infection studies." (PMID 32747682, 2020). "We confirmed that the majority of CD4+NK1.1+ T cells were truly type II NKT cells, since this population was reduced in CD1d-/- mice and did not expand in CD1d-/- mice relative to B6 and Jα18-/- mice after SA infection." (PMID 33312179, 2020). "Phenotypic analyses revealed that CD44hiCD62Lhi and CD44hiCCR7hi TCM cells in both CD4+ and CD8+ compartments were significantly higher in the luteolin-treated mice than in any of the other experimental groups post infection." (PMID 32956412, 2020). "Additionally, the finding that the TCR repertoire is higher in CD8 than in CD4 cells, suggests a larger clonal expansion of the CD8 cells taking part in the resolution of the infection." (PMID 32612615, 2020). "Additional to the highly efficient T cell infection route, MDM-mediated transfer of HIV-1 to T cells may help to seed the CD4+ memory latent reservoir." (PMID 32354203, 2020). "To identify potential soluble factors associated with HIV suppressive activity in our experimental system of single round infection, we first used a global approach of membrane-based cytokine array to screen the secretome profile of CD4/CD8 co-cultures versus CD4 mono-cultures." (PMID 32941545, 2020). "According to recent studies, crosstalk occurs between NK cells and macrophages, which plays an important role in anti-infection responses, and macrophages are activated by IFN-γ, which is mainly produced by NK cells and CD4+ T cells via increasing receptors such as CD80, CD86 and MHC II." (PMID 33327533, 2020). "Unbiased t-distributed stochastic neighbor embedding analysis gated on CD4+ T cells shows the small cluster of GC Tfh (Bcl6hiCXCR5hiPD-1hi) and the larger islands of hybrid Th1/Tfh cells (IFN-γ+IL-21+) generated in response to both infections." (PMID 32634740, 2020). "Unlike wild-type HIV-1, infection with Vpu-S52,56D and Vpu-S52,56N viruses did not result in a significant loss of PEX2, PEX7, PEX11B, or PEX13 in HeLa-CD4/CXCR4/CCR5 cells, macrophages, or T cells." (PMID 32127461, 2020). "In the none-infection group of infants and children, the CD4+IFNγ+TNFα+ double producers were identified to be similar across different ages (left)." (PMID 32849561, 2020). "However, after the infection, MFYcre mice exhibit excessive proportions of Ly6Chigh macrophages and Gr-1+ neutrophils, as well as elevated IFN-γ expression in effector CD4+ cells." (PMID 33240286, 2020). "A similar pattern emerged from analysis CAR activities over the time course of infection (E:T of 0.04:1); the bispecific CD4-R5Nt CAR was significantly more potent than the CD4 monospecific CAR, approaching the efficacy of the CD4-MBL CAR." (PMID 32523897, 2020). "In order to separate the influence of development and infection on the generation of cytokine co-expressing T-cells, we next analyzed the age dependency of the generation of these co-expressing CD4+ and CD8+ T-cells taking into consideration the infection history." (PMID 32849561, 2020).
infection (continued). "The results suggested that the CCR5 editing by Adv- AsCpf1-#4/#5 in primary CD4+T cells protected the cells from R5-tropic HIV-1YU-2 but not X4-tropic HIV-1NL4-3 infection compared with that of cells transduced with empty vector." (PMID 32670545, 2020). "During infection with parainfluenza, CXCR3 guides CD4+ T cells to the lungs." (PMID 32574175, 2020). "Expression of inhibitory receptors, PD-1 and CTLA-4, on global CD4+ T cells is almost universal in the early phase of the infection, regardless of the outcome." (PMID 33050486, 2020). "The immune cells were stained with (C–D) anti-CD1a and anti-HIV-1 mAbs for DCs, (E–F) anti-CD163 and anti-HIV-1 mAbs for macrophages (G–H), and anti-CD3, anti-CD4, and anti-HIV-1 mAbs for CD4+ T cells and the level of infection was assessed by flow cytometry (N = 11–15)." (PMID 32876566, 2020). "Individuals in large clusters were characterized by younger age, homosexual behavior, more recent infection, higher CD4 counts, and delayed/no ART (P < 0.001)." (PMID 33281803, 2020). "However, Cr-infection significantly decreased expression of B- and T-cell markers (CD19, CD45R; CD4, CD8a) in the spleen." (PMID 33076301, 2020). "In the case of EAE, LDV infection prior to MOG/CFA immunization blunted the production of IL-12 and IL-23 by cDC in the dLN, resulting in the absence of IFN-γ, IL-17, and GM-CSF production by MOG-specific CD4+ T cells, both in the periphery and in the CNS." (PMID 32265335, 2020). "None of the HIV-related factors such as duration of infection, exposure to ART, and CD4 count were associated with presence of MS in this population." (PMID 33194228, 2020). "To identify previously unrecognized cellular pathways that are associated with virus suppression by CD8+ T cells, we next assessed the transcriptional profile of eGFP- and eGFP+CD4+ T sorted subsets from CD4 mono—and CD4/CD8 co-cultures at three days post-infection." (PMID 32941545, 2020). "Strikingly, by d7pi, IL-5+ and IL-13+ CD4+ T cell numbers did not increase in Il17a-KO mice in response to infection." (PMID 32636457, 2020). "Five days after LM-GP66 infection, EZH2 expression by memory SM CD4 T cells was measured." (PMID 32999031, 2020). "Since IFN-γ production by CD4 T cells is a central immune mechanism in the clearance of both Cs and Ct, this result indicates that GI Cs and Ct infections are not likely to be cleared by the natural immune response and require antibiotic treatment." (PMID 32630694, 2020). "Our results showed that elevated expression and activity of ARG-1, but not ARG-2, were present in multiple cells post-infection, along with declined expression of T cell receptor CD3ζ chain in CD4+ and CD8+ T cells." (PMID 32029006, 2020). "Unlike in CD4+ T cells, perturbation to the B cell compartment were observed at both 0–3 months and 6–9 months, although not at 24–30 months after infection." (PMID 32886726, 2020). "These controller subgroups did not significantly differ in regard to CD4+ T cell counts or infection duration, but Nts were characterized by significantly higher VLs, despite overall low viremia." (PMID 31995767, 2020). "CD4+ T cells appear on day 7 after HSV-1 infection and peak on day 10 post-infection (dpi)." (PMID 32477330, 2020). "Second, HIV production is, on the whole, higher in BCL2+ CD4 T cells than in BCL2- T cells despite a similar infection frequency, suggesting but not proving the possibility that BCL2 expression favors survival of reactivated, virus producing cells." (PMID 33075109, 2020). "Only one study also measured the expression of transcription factors T-bet, Gata-3 and Foxp3 in CD4+ T cells following STM infection but the results were not fully conclusive." (PMID 33584671, 2020). "Infection with this L. major strain leads to the development of a non-healing lesion in C57BL/6 mice, a process that occurs despite the strong presence of IFN-γ producing CD4+Th1 cells." (PMID 33212818, 2020).
infection (continued). "In the mouse CD4+ T-cells, and to a lesser extent CD8+ T cells, appear to be more important in controlling primary Eimeria infection, whilst CD8+ T cells appear to be more important in secondary infections." (PMID 32175341, 2020). "TZM-bl cells were used as these are a HeLa cell derivative engineered to express high levels of HIV-1 receptor and coreceptor (CD4 and CXCR4, respectively) and contain β-galactosidase and luciferase regulated by the HIV-1 LTR promoter to quantitate infection (27, –, 29)." (PMID 32371599, 2020). "On the other hand, CD4+CD44+IFN-γ+IL-17+IL-2+ T-cells (R = −0.7133, p < 0.0001) and CD4+CD44+IFN-γ+TNF-α+IL-2+ T-cells (R = −0.6845, p < 0.0001) showed correlation with bacterial load only post-infection." (PMID 32545304, 2020). "Further, the number of 2W-specific CD4+ T cells reached a new set point in the liver following secondary infection, highlighting the ability of prime-boost strategies to bolster Ag-specific CD4+ T cell numbers for extended periods in non-lymphoid tissues." (PMID 32983171, 2020). "Tfh cells were evaluated before and after re-challenge of WT and Icos-/- mice to determine if the absence of ICOS impairs the ability of CD4+ T cells to promote a humoral response after re-infection." (PMID 32348365, 2020). "The concentration of major histocompatibility complex class II (MHCII), an extracellular complex that presents antigens to CD4+ T cells after phagocytosis, did not change between zero- and three-hours post-infection (16.5 ± 1.6% vs. 14.9 ± 0.4%, p = 0.9966)." (PMID 32882969, 2020). "The CD4+ EVs can potentially restrict HIV in several ways: acting as a decoy for CD4+ T-cells, neutralizing HIV-1 virions, or protecting neighboring T-cells from infection, ultimately inhibiting HIV-1 spread." (PMID 33096825, 2020). "In this study, we show that Ag-experienced (Ag-exp) CD4+ T cell exhaustion during Plasmodium yoelii nonlethal infection occurs alongside the reduction in mammalian target of rapamycin (mTOR) activity and restriction in CD4+ T cell glycolytic capacity." (PMID 32817333, 2020). "The lack of PD-L1 impairs the expansion of activated CD4+Ly6Chi T effector cells during infection and enhances the frequency of Tregs in the infected ear and in the draining lymph nodes." (PMID 33193363, 2020). "CD4 TRM cells are expanded in the lung and nasal tissue during infection of mice with B. pertussis." (PMID 33096737, 2020). "These may include mechanisms to avert activation-induced depletion of the CD4+ TCM compartment, which in turn may preserve and enhance the restorative capacity following infection." (PMID 32194543, 2020). "Antiretroviral therapy (ART) suppresses HIV replication, but does not cure the infection because replication-competent virus persists within latently infected CD4+ T cells throughout years of therapy." (PMID 30716099, 2019). "CD4+ cells isolated from mice infected intravenously or subcutaneously with 2W-GAS showed a Th17/Th1 ratio that was 40 times less than the intranasally infected mice, indicating that the Th17 response is dependent on the intranasal route of infection." (PMID 31119108, 2019). "Taken together, the results show that immunization with InsB can produce multifunctional Th1 CD4+ T cells, including CD8+ T cells, and that these reactions might remain for a long time after virulent Mtb strain infection." (PMID 30809214, 2019). "To rule out the possibility that high level of transfection reduces availability of target cells for infection, we mixed transfected and nontransfected 293T/CD4/X4 cells at 1:1 ratio and measured infection 48 h thereafter." (PMID 31027334, 2019). "In this way, the infection of myeloid cells is the bridge between the relatively hostile sites of virus acquisition (most notably the peripheral mucosal tissues) and the key target of HIV; CD4+ T cells." (PMID 31396206, 2019).
infection (continued). "Since the last report, recommendations to initiate ART have fundamentally changed; all individuals with HIV infections should be treated as early as possible after infection, regardless of CD4+ count." (PMID 30052811, 2019). "Although SEA did not affect cis-infection of CD4+ enriched T-cell blasts, it efficiently blocked DC-SIGN mediated HIV-1 trans-infection through the binding of Kappa-5 to DC-SIGN." (PMID 31487324, 2019). "While activated and proliferating CD4+ T lymphocytes are highly susceptible to infection and support efficient HIV-1 replication, resting CD4+ T cells are mainly non-permissive because of their low level of transcriptional activity." (PMID 31042779, 2019). "In studies of L. donovani infection in BALB/c mice, the parasite induced the initial expansion of IFN-γ-producing CD4+ and CD8+ T cells in the acute phase of the disease, the frequency of which was reduced after 21 days post-infection even with a robust parasite presence." (PMID 31889072, 2019). "Here we show that adding to this cohort 20 younger individuals with a shorter period of infection and aviremia and a higher CD4 count before ART, did not disrupt the hierarchical clustering." (PMID 31572392, 2019). "In rhesus macaques, the establishment of a productive simian immunodeficiency virus (SIV) infection in the genital mucosa required local chemokines, which facilitated recruitment of CD4+ T cells to the site of infection, and enabled SIV expansion and establishment of infection." (PMID 31144462, 2019). "However, it is generally accepted that the activation of the CD4+ and CD8+ responses are involved in the immune control of infection severity, and the neutralizing antibodies play little role in protection." (PMID 30658445, 2019). "We previously found that infection of cats with a non-pathogenic lentivirus from pumas (puma lentivirus, PLV, also known as FIVpco) provided protection from CD4+ T cell depletion during infection with a virulent host-adapted strain of FIV." (PMID 31500260, 2019). "Following the lytic phase of infection, latent (non-replicating) infection occurs primarily in CD4+ T cells (T-helper cells) that are capable of being transformed around 7 dpi." (PMID 31798630, 2019). "We also tested pseudoviruses carrying HIV-1 Envs from subjects without or with only minor neurological complications for infection of CD4-negative Cf2Th/CCR5 cells." (PMID 30415390, 2019). "We analyzed the reactivity of the vaccine-induced antibody responses against T. cruzi and T. rangeli, and profiled the activation of antigen presenting cells (APC), i.e., dendritic cells (DC) and macrophages (Mφ), and CD4+ and CD8+ T cells after vaccination and challenge infection." (PMID 31293599, 2019). "Interestingly, at early infection a significant proportion of IFN-γ and TNF-α producing cells predominantly from CD4+CD25− and CD4+FoxP3− T cell were observed." (PMID 31031744, 2019). "Depletion of CD4+ T cells resulted in a mild reduction in parasite-specific IgG levels antibody unlikely to be responsible for diminished resistance to infection." (PMID 31730667, 2019). "Although the CD4+ T cells in the lamina propria are considered the major target for HIV-1, infection of macrophages located in the lamina propria of the intestinal, penile urethral and vaginal mucosa has been described." (PMID 31866988, 2019). "In contrast, a significantly higher IL-7R+2W+CD4+ T cell population was observed LdCen−/− infection similar to our previously published results and no change in expression was observed upon LNA treatment (*p < 0.05)." (PMID 31608064, 2019). "We worked with a prototypic HIV-1 that uses CD4 and CCR5 cell-surface coreceptor to enter cells and is typical at the early stages of infection (isolate BaL) and a prototypic HIV-1 that uses CD4 and CXCR4 cell-surface coreceptor that often evolves at the late stages of infection (isolate LAI.04)." (PMID 31827089, 2019).
infection (continued). "Shan and colleagues also employed primary cell models to show latent HIV infection (as opposed to productive infection), preferentially occurs at the transition of CD4+ T cells from an effector to a memory state." (PMID 31507594, 2019). "Using a high CD4+ T cell count as a proxy for recent infection, our results suggest that BRAI may distinguish recent and long-term infection to a greater extent than LAg in the Estonian population." (PMID 31125356, 2019). "Our data show that HIV-1 replication is not necessary in APCs for productive trans infection of CD4+ T cells, given the more efficient B-cell-mediated trans infection compared with DC-mediated trans infection, confirming previous observations." (PMID 31304185, 2019). "Further 96–99% of NP311-specific CD4 T cells in the lungs, regardless of the infection dose, are CD49d+CD11ahi at day 7 p.i.." (PMID 31632414, 2019). "Given that infection with HIV has been shown to lead to modulation of T cell phenotypic profiles, we next determined the effect of HIV infection on the total CD4 T cell expression profiles of BTLA, CTLA-4, and PD-1 in individuals with LTBI and with active TB, using a Boolean gating strategy." (PMID 31497018, 2019). "Mouse infection models using BCG or HSV-2 showed that cutaneous infection with these microbes led to the generation of IL-3–producing CD4+ T cells, whereas i.v. infections did not." (PMID 31356170, 2019). "Using Foxp3-eGFP mice to accurately detect in vivo generated CD4+CD25+Foxp3+ Tregs, the infection with the S. aureus USA300 WT strain led to a significantly increased frequency (PBS: 11.2 ± 0.4%, WT: 17.6 ± 0.6%; mutant: 14.9 ± 0.6%) of Tregs in the spleen compared to PBS-treated mice." (PMID 31134074, 2019). "LPCs stimulated with FBCs from HIV-negative and HIV-positive MSM displayed significantly elevated CD8+ T cell activation at the end of infection, and frequencies of HIV-infected cells significantly correlated with both CD4+ and CD8+ T cell activation of stimulated LPCs." (PMID 30947289, 2019). "The greatest number of IL-17 or IFN-γ-secreting CD69+CD4+ TRM cells in the lungs and nose 7 days post challenge was induced by previous infection, followed by wP-immunization, while immunization with an aP vaccine did not induce cytokine production above control level." (PMID 30866771, 2019). "B-cell-mediated trans infection of CD4+ T cells was not significantly affected over 12 days by exposure to the drugs tested." (PMID 31304185, 2019). "Moreover, up to 24% of the naïve CD4+T cells also differentiated to induced T regulatory (iTreg) phenotype (CD25+FoxP3+) in vaccinated mice before and challenge infection (*p < 0.01)." (PMID 31293599, 2019). "HIV-1-exposed pDCs released higher IFNα compared to non-exposed pDCs, while blockage of pDC infection with a mAb against CD4 reduced IFNα secretion compared to an isotype control." (PMID 31114569, 2019). "The magnitude of CD4+ T-cell depletion following the second infection was reduced compared to the first infection (in A1Ifnar-/- mice) or absent (in A1Ifnar+/+ mice)." (PMID 31644426, 2019). "Thus, in vivo, both CD4+ and CD8+ T cells are capable of responding to jhp_0775-derived epitopes after infection as well as vaccination." (PMID 31758014, 2019). "Since SHIV envelope proteins (Envs) are derived from HIV-1, we tested more than 100 HIV-1 clade B Envs for infection of CD4-negative, CCR5+ Cf2Th/CCR5 cells." (PMID 30415390, 2019). "Together, these data indicate that IFN-γ-responses in LckcreIL-4Rα−/lox mice developed fully in the absence of IL-4Rα+ signaling on CD4+ T cells when compared with wild-type mice over the course of infection." (PMID 31475014, 2019). "Furthermore, it was discovered that S. Typhimurium CVCC541 promoted the proliferation and activation of CD4+ and CD8+ T cells at day 11 after infection." (PMID 30898022, 2019).